OR2L2 (olfactory receptor family 2 subfamily L member 2)
Description:
Odorant receptor.
Synonyms: OR2L12; OR2L4P; HTPCRH07; HSHTPCRH07; OR1-48
Tractability: Antibody: UniProt places it where antibodies can reach, with medium confidence; UniProt predicts a signal peptide or a membrane-spanning region; its Gene Ontology location is reachable by antibodies, with medium confidence.
Gene: Protein-coding gene on chromosome 1 (248,030,070 to 248,042,305, forward strand). Ensembl gene ENSG00000203663.
Subcellular location: Cell membrane
Pathways (Reactome):
Sensory Perception: Expression and translocation of olfactory receptors
Gene Ontology:
Molecular function: olfactory receptor activity; G protein-coupled receptor activity
Biological process: detection of chemical stimulus involved in sensory perception of smell; G protein-coupled receptor signaling pathway
Cellular component: plasma membrane; membrane
Genetic constraint (gnomAD): Loss-of-function variants: 1 observed, 0.34 expected, observed/expected ratio (o/e) 2.95. That is too few expected variants to judge how well the gene tolerates losing a copy. Missense variants: 370 observed, 377.52 expected, observed/expected ratio (o/e) 0.98, 90% interval 0.9 to 1.07. Synonymous variants: 155 observed, 134.9 expected, observed/expected ratio (o/e) 1.15, 90% interval 1.01 to 1.31.
Homologues: Orthologues: chimpanzee OR2L2 (98% identical), macaque OR2L2 (92% identical), dog OR2L5 (82% identical), dog OR2L3 (80% identical), dog OR2L3B (80% identical), mouse Or2l5 (79% identical), dog OR2L5C (79% identical), dog OR2L17 (78% identical), rat Or2l5 (78% identical). Paralogues in human: OR2L5 (90% identical), OR2L8 (86% identical), OR2L3 (85% identical), OR2L13 (71% identical), OR2AK2 (55% identical), OR2AJ1 (54% identical), OR2T27 (52% identical), OR2T1 (52% identical), OR2M2 (51% identical), OR2M3 (51% identical), OR2M5 (50% identical), OR2T4 (50% identical), and 80 more.